B4GALNT1 (beta-1,4-N-acetyl-galactosaminyltransferase 1)
Diseases named in the same sentence as B4GALNT1 in open-access papers (continued):
Sharing a sentence is not in itself a finding about the gene and the disease.
demyelination (1 paper, 2024). "In this study, we investigated the sensitivity to inhalational anesthetics in two models of demyelination—congenital (B4galnt1-null mice) and chemically induced (cuprizone-treated mice)." (PMID 39194711, 2024). "In this study, the age-dependent effects of inhalational anesthetics on two demyelination models were investigated: congenital (B4galnt1-null) and chemically induced (cuprizone)." (PMID 39194711, 2024).
ependymoma (1 paper, 2023). A WHO grade II, slow growing tumor of children and young adults, usually located intraventricularly. "In ependymoma, ST8S1A1 was downregulated, and B4GALNT1 was upregulated in hypomethylated samples." (PMID 37373053, 2023).
GM2 gangliosidosis (1 paper, 2025). A group of recessively inherited diseases characterized by the intralysosomal accumulation of G(M2) GANGLIOSIDE in the neuronal cells. "The aim of this study was to identify inhibitors for B4GALNT1 that may be developed for treatment of GM2 gangliosidosis but not cause symptoms of SPG." (PMID 40942141, 2025).
inflammatory bowel disease (1 paper, 2015). A spectrum of small and large bowel inflammatory diseases of unknown etiology. "B4galnt1 regulates postnatal development of colonic epithelial cells through the biosynthetic pathway of Sda blood group antigen, and is implicated in inflammatory bowel disease, colorectal and other types of cancer." (PMID 26420038, 2015).
Insulin resistance (1 paper, 2019). Increased resistance towards insulin, that is, diminished effectiveness of insulin in reducing blood glucose levels. "Specific inhibition of GM1 synthesis by targeting B4GALNT1 or inhibition of the interaction between GM1 and IR could be employed to develop new efficient therapeutic strategies for vascular insulin resistance." (PMID 31013778, 2019).
liposarcoma (1 paper, 2025). A usually painless malignant tumor that arises from adipose tissue. "CNA analysis implicated B4GALNT1 amplification as a GD2-promoting factor in dedifferentiated liposarcoma." (PMID 41424948, 2025).
liver cancer (1 paper, 2024). An epithelial or non-epithelial malignant neoplasm that arises from the liver. "Here, by analyzing the Chinese liver cancer population, our study confirms the prognostic value of B4GALNT1 across different ethnicities for the first time." (PMID 39616302, 2024).
male infertility (1 paper, 2023). The inability of the male to effect fertilization of an ovum after a specified period of unprotected intercourse. "Taking the cases that have no data available into consideration, it appears that B4GALNT1 deficiency may generally induce male infertility in humans as well." (PMID 36999634, 2023).
mast syndrome (1 paper, 2015). "Such conditions include HSP with thin corpus callosum (SPG11/15 mutations), SPG35/FA2H-associated HSP, Troyer syndrome (SPG20) and Mast syndrome (SPG21), SPG26/B4GALNT1, SPG30/KIF1A, SPG39/PNPLA6 and SPG46/GBA2." (PMID 25480570, 2015).
medulloblastoma (1 paper, 2025). A malignant, invasive embryonal neoplasm arising from the cerebellum. "For instance, medulloblastoma group 3 is characterized by predominant GM3 expression, which in the presence of ST8SIA1 and B4GALNT1 can be converted to GD2." (PMID 41424948, 2025).
myeloma (1 paper, 2019). "GM3 synthase B4GALNT1 is differentially activated from the pre-B cell stage to the terminally differentiated myeloma (plasma)cells, and GM2 synthase B4GALT has a high activity in lymphoblastoid cell lines and terminally differentiated myeloma cells only." (PMID 30761148, 2019).
retinoblastoma (1 paper, 2023). A malignant tumor that originates in the nuclear layer of the retina. "The sequences of B4GALNT1 and GAPDH, both in chromosome 12, are highly conserved in retinoblastomas, and in genomic regions away from areas that include frequent alterations such as RB1 (chromosome 13q) and MYCN (chromosome 2p)." (PMID 36148636, 2023). "In addition, the gene B4GALNT1 produces the ganglioside GD2, which is highly expressed in retinoblastoma." (PMID 36148636, 2023).
type 1 diabetes (1 paper, 2018). "Among these, the OR of 1.47 calculated for B4GALNT1 ranks it among the highest risk genes implicated in the predisposition to type 1 diabetes." (PMID 29671030, 2018). "Next, we discovered eight gene polymorphisms (ORMDL3, SPHK2, B4GALNT1, SLC1A5, GALC, PPARD, PPARG and B4GALT1) involved in sphingolipid metabolism that contribute to the genetic predisposition to type 1 diabetes." (PMID 29671030, 2018).
urothelial carcinoma (1 paper, 2025). A malignant neoplasm derived from the transitional epithelium of the urinary tract (urinary bladder, ureter, urethra, or renal pelvis). "In the Cancer Genome Atlas Urothelial Carcinoma (TCGA-BLCA) cohort, high levels of B4GALNT1 (beta-1,4-N-acetyl-galactosaminyltransferase 1) expression have been strongly linked to advanced clinical stages and poor prognosis." (PMID 40252176, 2025).
cancer (21 papers, 2015 to 2025). A tumor composed of atypical neoplastic, often pleomorphic cells that invade other tissues. "Overexpression or increased activity of B4GALNT1 is associated with several cancers including childhood neuroblastoma." (PMID 40593514, 2025). "Previous studies reported that B4GALNT1 was associated with the development of various types of cancers." (PMID 35935585, 2022). "We observed a statistically positive correlation between B4GALNT1 expression and the estimated infiltration value of cancer-associated fibroblasts for the TCGA tumors of BLCA-LumA, COAD, ESCA, HNSC, HNSC-HPV-, KIRC, PAAD, PRAD, READ, STAD, THCA, and THYM (Supplement 1A)." (PMID 35935585, 2022). "Additionally, the potential association between genetic alteration of B4GALNT1 and the clinical survival status of cases with different types of cancers was explored." (PMID 35935585, 2022). "Furthermore, glycosphingolipid synthase B4GALNT1, which has previously been associated with neuro-tumor progression and cancer stem cell characteristics by affecting glycosphingolipids, was upregulated in the high-abundance group." (PMID 34771607, 2021). "Additionally, we analyzed KEGG and HALLMARK terms of B4GALNT1 in pan-cancer." (PMID 35935585, 2022). "B4GALNT1 (be-ta-1,4-N-acetyl-galactosaminyltransferase 1) showed low expression in both MSCs and iPSCs compared to cancer cell lines." (PMID 39621192, 2025). "Considering the critical roles of GM2/GD2 in tumor progression, a growing body of research has focused on the roles of B4GALNT1 in cancers." (PMID 39616302, 2024). "Recent pan-cancer studies also revealed the prognostic value of B4GALNT1 in multiple cancer types and discussed its potential effects on tumor immunity." (PMID 39616302, 2024). "Copy counts for nucleus‐derived sequences of GAPDH and B4GALNT1 were significantly higher in the AH from patients with progressive disease, compared to the AH from progression‐free patients and control non‐cancer patients." (PMID 36148636, 2023). "To further illustrate the prognostic potential of B4GALNT1, we divided the cancer cases into high-expression and low-expression groups according to the expression levels of B4GALNT1, mainly using the datasets of TCGA." (PMID 35935585, 2022). "B4GALNT1 expression is related to poorer prognosis in patients, but the relationship is cancer-specific." (PMID 35935585, 2022). "The results in these cancers indicated that the expression of B4GALNT1 presented with significance in different tumor stages, which reveals the possible relevance of B4GALNT1 expression and tumor progression." (PMID 35935585, 2022). "The current study revealed that a correlation of B4GALNT1 expression with prognosis exists in multiple types of cancers." (PMID 35935585, 2022). "The TIMER2 approach was applied to analyze the expression status of B4GALNT1 among multiple types of cancers from the TCGA database." (PMID 35935585, 2022). "The potential molecular mechanism of B4GALNT1 in pan-cancer gene expression, prognosis, genetic alteration, immune infiltration, relevant cellular pathway, and sensitivity of targeted drugs for it was investigated." (PMID 35935585, 2022). "In the CCLE database, expression of JUP, ITGB4, ST8SIA5, ST8SIA1, ST3GAL2, ST3GAL5 and B4GALNT1 in pan-cancer were explored." (PMID 34402716, 2021). "In this study, we have not only shown how GM2/GD2 exacerbates tumors’ malignant characters by using B4GALNT1 artificial expression system, but also reconfirmed RNA-Seq is useful tool to find novel potential target in cancer." (PMID 31988291, 2020). "We used Univariate Cox analysis to evaluate the association of B4GALNT1 with disease-free interval (DFI), disease-specific survival (DSS), overall survival (OS), and progression-free interval (PFI) among 33 types of cancers." (PMID 35935585, 2022). "Therefore, we studied the relationship between B4GALNT1 expression and the level of immune cell infiltration in 33 cancer types from the TIMER database." (PMID 35935585, 2022).
cancer (continued). "Therefore, we used the EPIC, MCPCOUNTER, XCELL, and TIDE algorithms to examine the potential association between the infiltration level of different types of immune cells and B4GALNT1 gene expression in various types of TCGA cancers (Supplement 1)." (PMID 35935585, 2022). "Therefore, this study, for the first time, searched as many publicly available databases as possible and conducted an analysis of the pan-cancer role of B4GALNT1 in tumorigenesis." (PMID 35935585, 2022). "Furthermore, we combined the data from TCGA and GTEx databases to assess the differences of B4GALNT1 expression levels between 27 cancer types and corresponding normal tissues." (PMID 35935585, 2022). "Moreover, our results revealed that B4GALNT1 had great significance with multiple types of common immune checkpoint genes in pan-cancers." (PMID 35935585, 2022). "However, the degree of staining in DPM1, B4GALT3, B4GALT2, and B4GALNT1 was stronger in cancer tissues than normal tissues." (PMID 35356430, 2022). "A correlation of B4GALNT1 expression with prognosis exists in multiple types of cancers." (PMID 35935585, 2022). "Our study, using the database TIMER, EPIC, MCPCOUNTER, XCELL, and TIDE algorithms, revealed that B4GALNT1 expression in BLCA-LumA, COAD, ESCA, HNSC, HNSC-HPV-, KIRC, PAAD, PRAD, READ, STAD, THCA, and THYM is positively correlated with cancer-associated fibroblasts." (PMID 35935585, 2022). "Common immune checkpoint targets that have been reported for having a promising effect, including Lymphocyte activation gene-3 (LAG-3), T cell immunoglobulin and ITIM domain (TIGIT), and indoleamine 2,3-dioxygenase, have presented significance with B4GALNT1 in several cancers." (PMID 35935585, 2022). "Therefore, further research to discover the potential of B4GALNT1 in cancer treatment is of great necessity." (PMID 35935585, 2022). "The structure of B4GALNT1 allows for the prediction and testing of competitive inhibitors as potential therapeutics in diseases where overexpression is driving pathogenesis (such as cancers) or where GM2 substrate reduction would be beneficial (GM2 gangliosidoses)." (PMID 40593514, 2025). "Nevertheless, the role of B4GALNT1 in pan-cancer remains unclear." (PMID 35935585, 2022). "However, there is still a lack of pan-cancer evidence based on big clinical data on the correlation of B4GALNT1 with various types of tumors." (PMID 35935585, 2022).
tumor (19 papers, 2014 to 2026). "To further investigate the underlying molecular mechanism of the B4GALNT1 gene in tumor progression, we attempted to screen out the targeting B4GALNT1-binding proteins and the B4GALNT1 expression-related genes in order to establish a series of pathway enrichment analyses." (PMID 35935585, 2022). "B4GALNT1 expression is linked to tumorigenesis and the prognosis of tumor patients." (PMID 35935585, 2022). "Moreover, the expression of B4GALNT1 was associated with ImmuneScore and StromalScore in 21 and 27 tumor types, respectively." (PMID 35935585, 2022). "Further transwell assays supported that overexpressing B4GALNT1 in HCC tumor cells significantly promoted the infiltration of THP-1-derived human macrophages (p < 0.001)." (PMID 39616302, 2024). "To further verify the effects of B4GALNT1 on tumor progression and immune regulation, we generated a B4GALNT1-KO cell line and tested its tumor growth in a mouse model." (PMID 39616302, 2024). "Since the upregulation of B4GALNT1 in HCC tumor tissues has been previously reported, we first attempted to verify this aberrant upregulation in our collected samples and public datasets." (PMID 39616302, 2024). "Here, we identified SPP1 as the critical secretion factor for the process by which tumor B4GALNT1 modulates the recruitment or polarization of macrophages and Th2 cells." (PMID 39616302, 2024). "And we found that malignant cells conferred highest percentage of B4GALNT1-positive cells among all cell types, indicating the majority of B4GALNT1expression in tumor cells." (PMID 39616302, 2024). "The GSVA results also showed that B4GALNT1-positive malignant tumor cells exhibited higher MAPK signaling pathway activity compared to B4GALNT1-negative cells." (PMID 39616302, 2024). "Here, our in vivo data demonstrated that silencing B4GALNT1 significantly enhances the tumor-killing efficiency of the PD-1 targeting strategy, indicating that B4GALNT1 is a strong candidate for combined immune therapy approaches." (PMID 39616302, 2024). "To investigate the detailed roles of B4GALNT1 in altering HCC tumor microenvironment (TME), we performed bioinformatic analysis, and found that B4GALNT1 expression was positively correlated with the numbers of TAMs and Th2 cells in TME." (PMID 39616302, 2024). "Taken together, these findings demonstrate that B4GALNT1 is upregulated in HCC tumor tissues, and such upregulation predominantly occurred in malignant cells." (PMID 39616302, 2024). "Increased protein levels of B4GALNT1 in tumor tissues were also observed in Western Blot (WB) tests on 21 patients and immunohistochemistry (IHC) assays on 93 other patients (p < 0.001)." (PMID 39616302, 2024). "The survival status of tumor patients was significantly related to B4GALNT1 expression, but the correlations were tumor-specific." (PMID 35935585, 2022). "We then used the GEPIA2 tool to integrate all tumor expression data of TCGA and achieved the top 100 genes that correlated with B4GALNT1 expression." (PMID 35935585, 2022). "The genetic alteration status of B4GALNT1 in different tumor samples of the TCGA cohorts was evaluated." (PMID 35935585, 2022). "In a genetic alteration analysis, we observed that in all tumor cases, those with altered B4GALNT1 showed better prognosis in overall survival, disease-specific survival, and progression-free survival, but not disease-free survival." (PMID 35935585, 2022). "As the expression of B4GALNT1 showed a significant tumor-specific relationship with immune infiltration cell levels in multiple types of tumors, we further evaluated the relationship between B4GALNT1 expression and 47 common immune checkpoint genes." (PMID 35935585, 2022). "Meanwhile, the GEPIA database showed that JUP, ITGB4, ST3GAL2, ST3GAL5 and B4GALNT1 were higher expressed in tumor samples than in paired normal tissues." (PMID 34402716, 2021). "The effect of B4GALNT1 for tumor incidence in vivo was assessed by injecting GM2/GD2-positive SH4 cells into NSG mice." (PMID 31988291, 2020).
tumor (continued). "Consequently, B4GALNT1 is proposed to facilitate tumor-stroma interactions, ultimately driving the progression of MIBC." (PMID 40252176, 2025). "We subsequently explored the precise mechanisms in B4GALNT1 regulating tumor immunity." (PMID 39616302, 2024). "Notably, our xenograft model demonstrated that targeting B4GALNT1 not only inhibits tumor growth but also increases the efficacy of immunotherapeutic approaches." (PMID 39616302, 2024). "In conclusion, this study revealed the upregulation of B4GALNT1 in HCC tumor cells, which could be used as a valuable prognostic predictor, and revealed the functions of B4GALNT1 in microenvironment remodeling in HCC via the HES4-SPP1-TAM/Th2 axis." (PMID 39616302, 2024). "In addition, silencing B4GALNT1 was proved to enhance the tumor-killing efficiency of the programmed cell death protein 1 (PD-1)-targeting strategy in mouse model." (PMID 39616302, 2024). "Our data verified the aberrant upregulation of B4GALNT1 in HCC tumor tissues and tumor cells, which could be utilized as an independent prognostic factor and improve the predicting performance of traditional tumor node metastasis (TNM) system." (PMID 39616302, 2024). "Therefore, we next evaluated the effects of targeting B4GALNT1 on the tumor-killing efficiency of the PD-1-targeting strategy." (PMID 39616302, 2024). "Moreover, IHC staining of HCC tumor tissues from our cohort also revealed significant correlations of B4GALNT1 levels with the numbers of infiltrating CD163 + TAMs (R2 = 0.06, p = 0.019) and CD4 + T cells (R2 = 0.05, p = 0.038)." (PMID 39616302, 2024). "Although IHC images revealed that B4GALNT1 was expressed mainly in the cytoplasm of tumor cells, its positive staining in other cell types could also be observed (data not shown)." (PMID 39616302, 2024). "In addition, our data revealed a correlation between B4GALNT1 and PD-1 levels in tumor tissues, and strong crosstalk between B4GALNT1-positive malignant cells and PD-1-positive CD8 + T cells." (PMID 39616302, 2024). "Although this study did not directly investigate the immune effects of GD2, the upregulation of B4GALNT1 in tumor cells observed in our results could lead to an increase in GD2 levels." (PMID 39616302, 2024). "Therefore, SPP1 is critical for the effects of B4GALNT1 on the polarization and recruitment of M2 macrophages and Th2 cells, which eventually leads to immune escape and tumor progression in HCC." (PMID 39616302, 2024). "Moreover, we examined the expression level of B4GALNT1 in 21 tumor cell lines based on the data of the CCLE database." (PMID 35935585, 2022). "Therefore, although the specific biological mechanism of how B4GALNT1 regulates tumor-infiltration immune cells and how it affects the tumor microenvironment still lacks enough evidence, its role in tumor immunity deserves further investigation." (PMID 35935585, 2022). "In previous studies, B4GALNT1 expression-related gangliosides have been observed to play a vital role in tumor immunity: T cells compose a crucial part of tumor-infiltration lymphocytes, and T cell activation is triggered by their surface molecules, known as TCR, into regions on the cell membrane." (PMID 35935585, 2022). "We hypothesized that B4GALNT1 may enhance tumor induction and growth by increasing tumor vascularization." (PMID 31988291, 2020). "In xenograft-bearing mice treated with antibodies against PD-1, we observed significant enhancement of B4GALNT1 depletion on the tumor-killing effects of anti-PD-1 antibodies, indicating that targeting B4GALNT1 may be a valuable auxiliary approach for modifying current immunotherapy." (PMID 39616302, 2024). "In addition, the associated roles of B4GALNT1 in intracellular transport suggest that the effects of malignant cell-derived B4GALNT1 on tumor immunity might be achieved by the regulation of the transport or secretion of cytokines or chemokines." (PMID 39616302, 2024).